ENSG00000251861
Synonyms: LOC124900453
Gene: Small Cajal body-specific RNA gene on chromosome 1 (204,727,991 to 204,728,106, forward strand). Ensembl gene ENSG00000251861.
Gene Ontology:
Biological process: RNA processing
Cellular component: Cajal body; nucleolus